RET (ret proto-oncogene)
Diseases named in the same sentence as RET in open-access papers (continued):
Sharing a sentence is not in itself a finding about the gene and the disease.
tumor (continued). "RET alterations were assessed by several local testing methods, NGS using DNA or RNA, in tumor tissue or in circulating blood, or FISH in tumor tissue." (PMID 35422765, 2022). "Regorafenib inhibits kinases and cellular pathways involved in angiogenesis and tumor growth, such as the VEGFR1-3, FGFR1-2, c-KIT, PDGFRα/β, RET, and BRAF." (PMID 36612019, 2022). "As for tumor microenvironment, RES subtype exhibited increased recruiting activity of CD8 + T, T helper 1, and natural killer cells, and RET subtype with increased recruiting activity of CD4 + T and regulatory T cells in silico." (PMID 35879731, 2022). "It is a multikinase inhibitor targeting VEGFR1-3, MET, the TAM family of kinases (TYRO-3, AXL, MER), RET, ROS1, KIT, TRKB, FLT-3, and TIE-2, which are mostly involved in tumor growth, angiogenesis, and immune regulation." (PMID 36612019, 2022). "We performed next-generation RNA sequencing on WCM271 tumor tissue and identified CCDC6 as the RET gene fusion partner." (PMID 35510953, 2022). "Central circulating tumor DNA (ctDNA) analysis was also performed in patients for whom FISH was used, with the aim of identifying the RET fusion partners." (PMID 35962206, 2022). "Several sitravatinib targets, such as TAM receptors, MET, RET and KIT, are dysregulated in many types of cancer through overexpression or genetic alteration, and contribute to tumor development." (PMID 35767205, 2022). "When comparing the four categories of mutation status: indeterminate, RAS-mutant, BRAF-mutant, and RET/NTRK fusion, all variables were found to be statistically significant (P value < .05), except for sex and AJCC T (tumor size) category." (PMID 35015563, 2022). "NSCLC patients with recurrent metastatic disease are subsequently eligible for targeted systemic therapy if the tumor expresses clinically actionable genetic alterations such as EGFR, ALK, MET, RET, and ROS1." (PMID 35448189, 2022). "A RET p.D378_G385delinsE MTC was treated with selpercatinib and achieved partial response, with a maximum tumor reduction of 86%." (PMID 36091144, 2022). "Tumours harbouring mutations in genes such as EGFR and ERBB2, or gene rearrangements involving ALK, RET, or ROS1 are typically dependent on the oncogene for survival, with profound anti-tumour effects observed in response to the appropriate targeted therapy." (PMID 35326531, 2022). "A RET fusion can be a mechanism of secondary resistance since RET kinase domain activation leads to oncogenic signaling of the PI3K-AKT, JNKs, and BRAF–MEK–ERK pathways, thus promoting cell survival and tumor promotion." (PMID 35406400, 2022). "Subsequent studies illustrated that sorafenib inhibits activity of wild-type RET and oncogenic altered RET with some degree of selectivity to abrogate PTC tumor cell proliferation and growth in vitro and in vivo." (PMID 35957881, 2022). "Apart from a few exceptions (RET-PCPG P66) we found different iCNV patterns in chr13 and chr15 in a subset of the tumor cells; in P227 (SDHB-PCPG) we identified small variations in chr3 and chr17 but observed few intra-individual heterogeneities." (PMID 36046044, 2022). "A next‐generation sequencing assessment of tumor tissue identified a CCDC6‐RET rearrangement, so the patient started treatment with a selective RET inhibitor." (PMID 36202602, 2022). "According to ATA guidelines, treatment with TKIs targeting both RET and VEGFR TK should be considered the treatment of choice in patients with significant tumor burden and advanced MTC." (PMID 35872981, 2022). "Lenvatinib, which inhibits VEGFR1-3, RET, Kit, and FGFR1-3, demonstrated preclinical efficacy in various human tumor xenograft models." (PMID 35054474, 2022). "Regorafenib is an oral multikinase inhibitor of several protein kinases, including kinases involved in tumor angiogenesis (VEGFRs 1–3), oncogenesis (KIT, RET, RAF1, BRAF, and BRAFV600E), and development of the tumor microenvironment (PDGFR and FGFR)." (PMID 33337518, 2021).
tumor (continued). "Lenvatinib inhibits tumor growth by blocking several targets, including VEGFRs, PDGFRs, FGFs, SCF, PDGFR, c-KIT, and RET." (PMID 33669204, 2021). "Accordingly, in vivo target inhibition (IVTI) confirmed the ability of Pz-1 to reduce phosphorylation of RET and TRKA, and some downstream signalling targets, at the doses used for tumour growth inhibition." (PMID 34373541, 2021). "As follows from literature data, the frequency of RET/PTC3 declined in the Chernobyl PTC over time, as did tumor aggressiveness as described in our recent analysis." (PMID 34282777, 2021). "Levatinib is a MKI targeting VEGFR 1–3, fibroblast growth factor receptor 1–4, platelet derived growth factor receptor, RET and KIT with similar anti-tumor activity to sorafenib." (PMID 33923463, 2021). "Regorafenib is an oral MKI affecting vasculature and tumor microenvironment with targeting of specific kinase proteins (VEGFR1,2,3, PDGFR, FGFR, KIT, BRAF, and RET)." (PMID 34069999, 2021). "This drug not only directly suppresses tumor cells proliferation by blocking RAF/MEK/ERK and JAK/STAT signaling pathways, but also inhibits tumor angiogenesis by targeting VEGFRs, PDGFR-β, c-Kit, FLT3, RET." (PMID 34381735, 2021). "However, without biological confirmation, the RET mutation remains a variant of unknown significance in this tumour." (PMID 34493325, 2021). "In RET positive MTC, among several miRNAs identified, eight were up-regulated and one of them, miR-153-3p, was found to have tumor suppressor function, increasing the antiproliferative efficacy of cabozantinib by acting on factors involved in the mTOR pathway." (PMID 33806299, 2021). "The in vitro cabozantinib screen was aligned with MET and RET expression and only showed efficacy in MET and RET positive LuCaP 93 cells, demonstrating that cabozantinib can elicit direct effects on SCNPC tumor cells driven by MET or RET activity." (PMID 33471819, 2021). "Regorafenib targets VEGFR1-3, TIE2, KIT, RET, RAF, PDGFR and FGFR, among other kinases, regulating tumor angiogenesis and tumor microenvironment and showing therapeutic benefit in various malignancies." (PMID 33800796, 2021). "To correlate RET inhibition to drug plasma concentration, we harvested MZ-CRC-1-induced tumour tissues and plasma after 2, 4, 8 and 24 h following the last dose of Pz-1." (PMID 34373541, 2021). "Lenvatinib, used as the first-line treatment for HCC tumors, represses tumor cells by targeting FGF/FGFR, RET protooncogene, and cKIT." (PMID 33735820, 2021). "Regorafenib inhibits multiple tyrosine kinases involved in tumor angiogenesis (VEGFR1-3, TIE2), oncogenic transformation (KIT, RET, RAF1, BRAF), and shaping tumor microenvironment (PDGFR, FGFR)." (PMID 34527573, 2021). "In xenograft models, orally administered Pz-1 almost completely inhibited RET- and TRKA-mutant tumours at 1–3 mg/kg/day but showed a reduced effect on RET/TRKA-negative cancer models." (PMID 34373541, 2021). "We present evidences that GIPC2 upregulates p27 and suppresses PPGL cell proliferation and tumor growth both in vitro and in vivo, and we propose a GIPC2-based mechanism through which sporadic and RET- and SDHB-related hereditary PPGLs develop." (PMID 33947839, 2021). "A possible reason is the wide range of tumor cell targets affected (VEGF, VEGFR1–3, FGFR1–4, PDGFRα, KIT, and RET)." (PMID 34630336, 2021). "Cabozantinib plays important roles in tumor cell proliferation and tumor neovascularization targeting MET, vascular endothelial growth factor receptor (VEGFR), AXL, and RET." (PMID 33194654, 2020). "Here, the authors use proteogenomic approaches to analyse the primary tumour and lymph node metastases from a PTC patient and report an oncogenic RET fusion, and potential druggable targets from the ubiquitin signaling machinery for treating human PTCs." (PMID 32345963, 2020).
tumor (continued). "In summary, our molecular data together with a confirmed tumor response to the selective RET inhibitor LOXO-292, suggest that this patient's ATC was driven by the identified CCDC6-RET gene fusion." (PMID 32292131, 2020). "Ninety percent of the tumours with these gene rearrangements were native KRAS, with a high proportion of MSI-H: 86.4%, 45.5% and 14.3% of the tumours with NTRK1, RET and ALK fusions, respectively." (PMID 32418154, 2020). "Of the 604 patients in the TCGA cohort, we focused on 377 patients who have a complete set of information including age, gender, tumor site, nodal and tumor staging classification, GDNF, NCAM, GFRA and RET mRNA expression data for multivariate analysis." (PMID 32084217, 2020). "Conversely, regorafenib, a novel oral MKI, blocks several protein kinases involved in the tumor angiogenesis (VEGFR-1, -2, and -3), tumor growth (KIT, RET, RAF-1, and BRAF), and metastasis (PDGFR-β, FGFR1) of cancer cells." (PMID 32466169, 2020). "By employing proteomics, we further demonstrated that several members of the ubiquitin signaling machinery are deregulated in both tumor and LN metastatic lesions and interestingly, we detected high HUWE1 expression in RET transformed cells." (PMID 32345963, 2020). "In RET or EGFR expressing models, vandetanib showed a remarkable tumor regression, an effect ascribed to inhibition of RET or EGFR phosphorylation and downstream signaling pathways." (PMID 35582269, 2019). "Thus, in the present study, the role of prolonged leptin exposure in tumor progression and/or expansion, as it may occur in vivo in TC patients with high BMIs, was first analyzed in two PTC-derived cell lines carrying RET/PTC1 (TPC-1) and BRAF (K1) mutations which both express OB-R." (PMID 30906321, 2019). "Expression analysis further revealed the dramatic upregulation of RET and NTRK1 fusion transcripts in the tumours relative to their matched normal tissue." (PMID 31653970, 2019). "Despite the limited knowledge about the function of the 2 RET isoforms, RET51 seems to be more important in tumor development." (PMID 35582269, 2019). "In MCF-7 cells, the treatment with the TKI vandetanib was effective on tumor growth; this response is eliminated by dual knockdown of RET and EGFR, thus establishing a link between expression of RET/EGFR and response to TKIs." (PMID 35582269, 2019). "It is worth noting that the number of tumours exhibiting BRAF K601E, TERT, RET/PTC1, and PAX8-PPARγ were too low to establish statistical significance." (PMID 31623671, 2019). "In order to offset the time for tumor formation, 0.5×106 cells were injected for NCOA4-RET, whereas 5×106 cells were injected for ΔRET and RETamp in athymic nude mice." (PMID 30446652, 2018). "CCDC6 has been involved in different rearrangements with several tyrosine kinases (RET, PDGFRb, ROS1, FGFR2) in several tumours (thyroid, lung, leukemia, breast, iCCA)." (PMID 29455670, 2018). "The patient showed a dramatic response to vandetanib, a type I RET TKI, with reduction in her tumor size from 20 to 7 mm in diameter at 12 weeks." (PMID 29434222, 2018). "Tumor protein, collected at the end of treatment on day 14 for NCOA4-RET and ΔRET, revealed significant reduction in the fusion protein levels and downstream PI3K-AKT signaling for the cabozantinib-treated groups as measured by western blot." (PMID 30446652, 2018). "To understand the oncogenic role of RET fusions in other cancer types, we screened the transcriptomes of a diverse set of 273 PDX samples from 20 different tumor types for RET fusions using RNA-seq." (PMID 30038711, 2018).
tumor (continued). "Interestingly, recent studies indicate that increased expression of wildtype RET occurs in an even larger pool of NSCLC, where it may be linked to poor tumor differentiation, suggesting that, in addition to RET fusions, GFL-RET signaling may also contribute to these tumors." (PMID 30666215, 2018). "Regorafenib is a different oral MKI that potently blocks multiple protein kinases involved in tumor angiogenesis (VEGFRs 1–3, TIE2), oncogenesis (KIT, RET, RAF-1, BRAF), metastasis (VEGFR3, PDGFR, fibroblast growth factor receptor), and tumor immunity (CSF1R)." (PMID 29291014, 2017). "Because of the nodular thyroid and a 13-mm tumor of the left adrenal gland, and a suspicion of MEN2 syndrome, genetic analysis of the RET gene was also performed in 50-year-old female patient with carcinoid of the stomach." (PMID 28647780, 2017). "Establishment of native tumor cell lines with other RET-fusions, including TRIM33-RET, CLIP1-RET, and ERC1-RET, is also warranted." (PMID 29088743, 2017). "Another RET inhibitor cabozantinib is effective against a subset of NB cells in vitro by decreasing RET and ERK phosphorylation and cabozantinib inhibits tumor growth in vivo, suggesting that targeting RET is a promising treatment strategy in NB." (PMID 29262623, 2017). "Regorafenib, an oral mutikinase inhibitor, can inhibit activity of several protein kinases, including those involved in tumor proliferation (KIT, PDGFR and RET), tumor angiogenesis (VEGFR1-3, TIE2), and tumor microenvironment (PDGFR-B, FGFR)." (PMID 28915719, 2017). "The second cluster contained the kinase signalling subgroup including the RET, NF1, TMEM 127 and MAX mutant tumours." (PMID 29166454, 2017). "However, these mutations are not uniform among the various cell subpopulations, suggesting that the tumor may be of polyclonal origin or that the RET mutations are not the initial events in MTC tumorigenesis." (PMID 26829565, 2016). "In RET negative tumors, mutations of HRAS or KRAS are recurrently observed, and exome-sequencing of MTCs support that the RET and RAS pathways are prominent drivers in this tumor type." (PMID 26870890, 2016). "The observed co-expression of RET and EGFR in MLS prompted further investigation of RTKs as possible drug targets and their role in tumor development." (PMID 26595521, 2016). "Moreover, given the increasing number of cancers turned out to be associated with either rearranged or mutated forms of the RET receptor or RET gene over-expression, studies similar to that presented here might be fruitfully carried out in patient sets affected with different RET-related neoplasia." (PMID 27034161, 2016). "There are variations in the prevalence of RET/PTC oncogenes in PTC, but the highest frequency was detected in tumours occurring in children after radiation exposition." (PMID 27703585, 2016). "Oncogene RET/PTC1 has been reported to activate the production of pro-inflammatory cytokines, which in turn contributes to tumor growth and invasion." (PMID 26684869, 2015). "In our study, the average frequency of the RET break-apart probes 23.9 % (range, 14.8–37.8) and KIF5B-RET fusion 44.4 % (range, 22.2-72.4)in 9 tumor tissues." (PMID 26268359, 2015). "RET, NF1 and sporadic tumours (Cluster C2A) displayed a high frequency of 1q and 3q deletions, and a significant enrichment of 17q11 deletions (NF1 locus)." (PMID 25625332, 2015).
tumor (continued). "RET/PTC3 transcriptional products were found to be inhibited in tumours treated by siRNA RET/PTC3-SQ NPs (p<0.001) and these results were more significantly pronounced once we focused on RET/PTC3 protein expression in Western blot which was completely reduced." (PMID 24759995, 2014). "RET Tyr791Phe and SDHC Pro110Ser were verified by Sanger sequencing in both blood and tumour tissues." (PMID 23781326, 2013). "By 4 months after injection, each mouse (n=9) had developed a tumor at the site of FRTL (RET/PTC1) cell injection, and the mean of the maximum tumor diameter was 24±4.5 mm." (PMID 24014739, 2013). "Vandetanib (ZACTIMATM) is a once-daily oral anticancer drug that selectively targets VEGFR-dependent tumor angiogenesis and REarranged during Transfection (RET)- and epidermal growth factor receptor (EGFR)-dependent tumor cell proliferation and survival." (PMID 19946413, 2009). "In the RET/PTC3 mice, true tumours were already visible in 16% of the cases, either at 6 months and most often at 10 months." (PMID 18985036, 2008). "ZD6474 displays antitumour efficacy by directly inhibiting tumour cell proliferation and survival via EGFR and RET inhibition, as well as tumour angiogenesis via VEGFR inhibition." (PMID 17912240, 2007). "This unique case of a collision tumor of thyroid, including component of an MTC deals with the value of RET gene analysis and therapeutic implications in the index case and in family members." (PMID 17939859, 2007). "Increasing evidence indicates that oncogenic drivers, including EGFR, ALK, KRAS, MET, RET, and BRAF, actively shape the tumor immune microenvironment (TIME) by regulating antigen presentation, immune cell infiltration, cytokine signaling, metabolic programs, and immune checkpoint expression." (PMID 42079655, 2026). "Unlike MKIs, pralsetinib inhibited RET-driven tumour growth without VEGFR2 inhibition, potentially reducing off-target toxicities." (PMID 40332222, 2025). "Importantly, larotrectinib and entrectinib, both NTRK inhibitors, and selpercatinib, a RET TKI, have achieved tumor tissue‐agnostic indications against their respective targeted RTKs." (PMID 39950716, 2025). "Furthermore, the combination of RET and EGFR inhibitors showed synergistic antitumor activity in vitro and hindered tumor growth in mouse models with resistant cell xenografts." (PMID 40405293, 2025). "In contrast, docking analyses with four key anti-tumor targets: VEGFR2 (PDB ID: 3VO3), MET (PDB ID: 3DKC), RET (PDB ID: 2IVU), and Trk-A (PDB ID: 6PL3) revealed only weak interactions, including Pi-Anion, Pi-Alkyl, and Pi-Cation interactions, rather than strong hydrogen bonding." (PMID 40257021, 2025). "Indeed, lenvatinib acts by inhibiting multiple receptor tyrosine kinases, including VEGFR1–3, FGFR1–4, PDGFRα, RET and KIT, thereby impairing angiogenesis and tumor proliferation." (PMID 40507289, 2025). "Regardless of the tumor type, the mutation frequencies of CD74, FGFR1, and RET were significantly greater in patients with NRG1 fusion than in patients without NRG1 fusion." (PMID 40730881, 2025). "Moreover, when organ‐specific carcinogenicity was analysed using the ROSC‐Pred calibrated for rodents, RET, B[a]P and DMBA were predicted to induce tumours in different organs or tissues, such as skin, lung, liver, and kidney." (PMID 40211435, 2025). "Notably, upfront combination therapy with RET and EGFR inhibitors prevents compensatory EGFR activation, which otherwise contributes to tumor regrowth and resistance to RET inhibitors." (PMID 40405293, 2025). "We predicted RET inhibitors pralsetinib and selpercatinib among the top ten most effective in both pituitary and lung ACTH-secreting tumors, with the RET gene upregulated in 15/16 pituitary and 6/6 lung ACTH-secreting tumor cases investigated." (PMID 40002253, 2025). "Finaly, the tumor mutational burden (TMB) was low, and no abnormalities were detected in BRAF, NRAS, HRAS, NTRK1/2/3, RET, or TERT." (PMID 40277780, 2025).